MINDY4 (MINDY lysine 48 deubiquitinase 4)
Description:
Probable hydrolase that can remove 'Lys-48'-linked conjugated ubiquitin from proteins.
Synonyms: C7orf67; FAM188B; FLJ22374
Tractability: No criterion of Open Targets' tractability assessment is met for any kind of drug.
Gene: Protein-coding gene on chromosome 7 (30,771,417 to 30,892,387, forward strand). Ensembl gene ENSG00000106125.
Subcellular location (Human Protein Atlas): Cytosol; Vesicles
Gene Ontology:
Molecular function: cysteine-type deubiquitinase activity; K48-linked deubiquitinase activity
Biological process: protein K48-linked deubiquitination
Cellular component: cytosol
Genetic constraint (gnomAD): Loss-of-function variants: 59 observed, 80.81 expected, observed/expected ratio (o/e) 0.73, 90% interval 0.59 to 0.91. The upper end of that interval is the gene's LOEUF score, 0.91, which puts it in group 3 of 6, group 1 being the genes least tolerant of losing a copy. Missense variants: 879 observed, 920.84 expected, observed/expected ratio (o/e) 0.95, 90% interval 0.9 to 1.01. Synonymous variants: 366 observed, 361.45 expected, observed/expected ratio (o/e) 1.01, 90% interval 0.93 to 1.1.
Homologues: Orthologues: chimpanzee MINDY4 (97% identical), macaque MINDY4 (96% identical), pig MINDY4 (82% identical), dog MINDY4 (81% identical), guinea pig MINDY4 (77% identical), rabbit MINDY4 (76% identical), mouse Mindy4 (74% identical), rat Mindy4 (72% identical), tropical clawed frog mindy4 (48% identical), zebrafish mindy4 (41% identical), Drosophila melanogaster CG14142 (15% identical). Paralogues in human: MINDY4B (20% identical), MINDY3 (15% identical).
Diseases named in the same sentence as MINDY4 in open-access papers:
MINDY4 is named in the same sentence as 18 diseases in open-access papers, as found by Europe PMC text mining. Sharing a sentence is not in itself a finding about the gene and the disease. The quoted sentences say what the papers report.
cancer (5 papers, 2018 to 2026). A tumor composed of atypical neoplastic, often pleomorphic cells that invade other tissues. "The MINDY4 gene, also known as MINDY Lysine 48 Deubiquitinase 4, is implicated in the development of pathological conditions such as cancer and neurological disorders." (PMID 39765701, 2024).
MINDY4 also shares sentences with these, for which no sentence is quoted: tumor (5 papers); colorectal cancer (3); lung carcinoma (3); colon cancer (2); atherosclerosis (1); autoimmune disease (1); chondrosarcoma (1); gastric cancer (1); hepatocellular carcinoma (1); leukemia (1); lung adenocarcinoma (1); lymphoma (1); Machado-Joseph disease (1); neurological disorders (1); squamous cell carcinoma (1); squamous cell lung carcinoma (1); urolithiasis (1).